ANXA1 (annexin A1)
Diseases named in the same sentence as ANXA1 in open-access papers (continued):
Sharing a sentence is not in itself a finding about the gene and the disease.
hepatocellular carcinoma (21 papers, 2012 to 2024). A malignant tumor that arises from hepatocytes. "Elevated expression of ANNEXIN A1 predicts poor prognosis in human hepatocellular carcinoma and enhances cell malignant phenotype." (PMID 34340715, 2021). "The role of AnxA1 in polarizing macrophages towards the M2 phenotype in hepatocellular carcinoma has also been described." (PMID 34571894, 2021). "In fact, in an antithrombin III SV40 T large antigen (ASV) transgenic mouse model that constitutively develops hepatocellular carcinoma, high ANXA1 levels precede tumour development." (PMID 29614751, 2018). "ANXA1 is overexpressed in breast cancer and hepatocellular carcinoma but is markedly down-regulated in esophageal and head and neck carcinomas." (PMID 25490767, 2014). "In hepatocellular carcinoma (HCC), it has been shown that the AnxA1 N-terminal peptide is responsible for the polarization of macrophages towards the M2 phenotype, by signaling through FPR2 and by eliciting the activation of ERK, Akt, and NFkB." (PMID 34208346, 2021). "The results were further validated by RT-PCR, western blot, flow cytometry or immunofluorescent staining which revealed that prominin-1, annexin A1, annexin A3, transgelin, creatine kinase B, vimentin, and EpCAM were indeed highly expressed in the CD133-positive hepatoma cells." (PMID 23170877, 2012). "This contest allowed us to hypothesize that ANXA1 could affect the macrophages by activating its receptor FPR, as described in the hepatocellular carcinoma where this protein is able to enhance the differentiation into M2 macrophages via FPR2 and supports their expression of IL-10." (PMID 34681678, 2021). "Annexin A1 was recently reported to be highly expressed in CC, but not in hepatocellular carcinoma." (PMID 26774260, 2016). "However, ANXA1 expression, either at mRNA level or at protein level, was not changed significantly in colorectal and hepatocellular carcinomas compared with that in the surrounding benign tissues (D and 2 fifth to sixth panel)." (PMID 25038797, 2014). "Similarly, high ANXA1 expression correlated with advanced TNM stage and poor survival of human hepatocellular carcinoma (HCC) patients." (PMID 27941907, 2016). "However, the trend of ANXA1 up-regulation in tumors was not significant in colorectal and hepatocellular adenocarcinoma, which may be due to limited sample numbers." (PMID 25038797, 2014).
ischemic stroke (21 papers, 2016 to 2025). A stroke disorder caused by obstruction of blood flow to the brain, due to thrombotic (local blood clot formation) or embolic (due to a blood clot or other material traveling from another site) event. "In studies of ischemic stroke, nuclear accumulation of ANXA1 in neurons and microglia was associated with neuronal apoptosis and microglial polarization." (PMID 40785117, 2025). "In CD, ANXA1 has shown protective effects in ischemic stroke and intracerebral hemorrhage by modulating inflammation and platelet function." (PMID 41208642, 2025). "Meanwhile, one study found that dessuccinylation of ANXA1 inhibited the protective effect of SUMOylated ANXA1, which instead led to neuronal cell damage after ischemic stroke." (PMID 41208642, 2025). "Nevertheless, few therapeutic interventions targeting ANXA1 in microglia for ischemic stroke have been conducted." (PMID 37908731, 2023). "Our previous study showed that SIRT5 bound to and desuccinylated ANXA1 at K166, which was sufficient to induce neuroinflammatory and neurological function damage after ischemic stroke." (PMID 38093788, 2023). "It has already been demonstrated that Annexin-A1 has anti-inflammatory and protective action after ischemic stroke and it is also able to inhibit both acute and chronic inflammation, promoting M2 microglial polarization." (PMID 37508918, 2023). "The therapeutic potentials of AnxA1 and its peptide Ac2–26 have also been extensively demonstrated in experimental models, such as in allergic conjunctivitis, and in ischemic stroke models." (PMID 35798730, 2022). "It has been demonstrated that nuclear translocation of ANXA1 is involved in neuronal apoptosis after ischaemic stroke and induces retinal ganglion cell apoptosis after ischaemia–reperfusion injury through the p65/IL-1beta pathway." (PMID 35415239, 2022). "In a previous study, we identified that SENP6 aggravated neuronal apoptosis by de-SUMOylating ANXA1 after ischaemic stroke." (PMID 35869493, 2022). "In contrast, suppression of SIRT5-mediated desuccinylation of ANXA1 effectively inhibits neuroinflammation and improves neurological function after ischaemic stroke." (PMID 36517900, 2022). "Rationale: Annexin-A1 (ANXA1) has previously been proposed to play a crucial role in neuronal apoptosis during ischemic stroke injury." (PMID 34158860, 2021). "In this study, we elucidated the effects of S100A11 on protecting against neuronal apoptosis induced by ANXA1 nuclear translocation after ischemic stroke." (PMID 29844306, 2018). "The subcellular location of annexin A1 (ANXA1) determines the ultimate fate of neurons after ischemic stroke." (PMID 29844306, 2018). "Previous data have suggested that the nuclear translocation of annexin 1 (ANXA1) is involved in neuronal apoptosis after ischemic stroke." (PMID 27584794, 2016). "The protective role of ANXA1 nuclear translocation in this context differs from its reported pro‐inflammatory function in ischemic stroke models, suggesting that the functional consequences of ANXA1 nuclear translocation are highly dependent on the underlying pathophysiological conditions." (PMID 40785117, 2025). "The upregulated expression of ANXA1 emerging from our data suggests that this protein could have a protective role after ischemic stroke, reducing neuroinflammation and related brain damage even after an average of 2.6 years from the ischemic event." (PMID 37508918, 2023). "For example, our recent study demonstrated that SENP6-mediated deSUMOylation of ANXA1 could induce its nuclear translocation and trigger neuronal apoptosis after ischaemic stroke." (PMID 36517900, 2022).
ischemic stroke (continued). "However, there is evidence suggesting that nuclear translocation of ANXA1 can enhance the production of proinflammatory factors in microglia following ischaemic stroke." (PMID 36517900, 2022). "Additionally, our previous study found that SENP6 in neurons promoted neuronal apoptosis by mediating the de-SUMOylation of Annexin-A1 (ANXA1) after ischaemic stroke." (PMID 35869493, 2022). "However, the role of ANXA1 succinylation and the key enzymes which regulate the succinylation status of ANXA1 during ischaemic stroke remain poorly understood." (PMID 36517900, 2022). "Whether SENP6-mediated ANXA1 deSUMOylation has a role in microglial polarization and the inflammatory response after ischemic stroke warrants future investigation." (PMID 34158860, 2021). "Anxa1 (Annexin A1) was shown to have multiple functions, and taking into account its anti-inflammatory effects, it was suggested to be neuroprotective during ischemic stroke injury." (PMID 34944656, 2021). "As SUMOylated ANXA1 protects against ischemic stroke through different mechanisms in neurons and microglia, we hypothesized that increased SUMOylation of ANXA1 in neurons and microglia at the same time would be even more potent." (PMID 34158860, 2021). "Exogenous ANXA1 functions through FPRs to initiate endogenous pro-resolving and anti-inflammatory pathways following ischemic stroke, but the roles of its peptides in microglia remain unclear." (PMID 29662435, 2018). "In particular, the exact mechanism of exogenous ANXA1 in microglia affected by ischemic stroke remains unknown." (PMID 29662435, 2018). "Collectively, these observations provide a more comprehensive understanding of ANXA1 function in cell apoptosis after OGD/R and strongly suggest that decreasing nuclear ANXA1 migration might be a useful therapeutic approach for treating ischemic stroke." (PMID 27584794, 2016). "This process prevents ANXA1 from being recruited to the membrane and secreted outside the cell, resulting in an overactive response from microglia, increased production of proinflammatory cytokines and chemokines, and ultimately damage to neuronal cells in cases of ischemic stroke." (PMID 38961424, 2024). "Moreover, our previous study reported that the cell‐penetrating peptide Tat‐NTS inhibits the binding of ANXA1 to importin β, significantly inhibiting the nuclear transport of ANXA1 in neurons and thereby protecting against ischemic stroke‐induced neuronal damage." (PMID 38093788, 2023). "Importantly, improving SIRT5 significantly promotes ANXA1 nuclear translocation and suppresses ANXA1 membrane recruitment, followed by microglial hyperactivation, ultimately leading to excessive neuroinflammation and neuronal damage after ischaemic stroke." (PMID 36517900, 2022). "However, whether and how the deSUMOylation of ANXA1 contributes to neuronal damage in the brain in response to ischemic stroke injury remains unclear." (PMID 34158860, 2021). "Therefore, studies aiming to identify the factors that specifically block the nuclear translocation of ANXA1 may provide promising targeted strategies for the treatment of ischemic stroke." (PMID 29844306, 2018). "Notably, the desuccinylation of ANXA1 blocks its membrane recruitment and extracellular secretion, resulting in the hyperactivation of microglia and excessive expression of proinflammatory cytokines and chemokines, ultimately leading to neuronal cell damage after ischaemic stroke." (PMID 36517900, 2022). "We provide experimental evidence that the interaction between SIRT5 and ANXA1 increases and that SIRT5 mediates the desuccinylation of ANXA1 after ischaemic stroke." (PMID 36517900, 2022).
ischemic stroke (continued). "ANXA1 via its receptor FPR2 has been shown to mitigate cerebrovascular injury by limiting immune cell infiltration and pro-inflammatory thrombotic cytokine production in mouse models of ischemic stroke." (PMID 37208759, 2023). "In summary, our results demonstrate that the lack of AnxA1 leads to aberrant platelet recruitment and aggregation in the brain after ischemic stroke and that exogenous administration of AnxA1 is a powerful proresolving mediator of thromboinflammation." (PMID 31154815, 2019). "Previous data showed that SUMOylated ANXA1 upregulation promoted the anti-inflammatory polarization of microglia subjected to OGD/R injury and that overexpression of SUMOylated ANXA1 specifically in microglia showed robust neuroprotection against ischemic stroke." (PMID 34158860, 2021). "In a mouse model of ischemic stroke, S100A11 exerts neuroprotective effects, and upregulation of S100A11 protected against neuronal apoptosis by interaction with ANXA1 through the nuclear translocation signal (NTS) of ANXA1, thereby blocking ANXA1 nuclear translocation." (PMID 34179021, 2021). "We demonstrated a previously unidentified mechanism by which SENP6-mediated ANXA1 de-SUMOylation regulates microglial polarization and our results strongly indicated that in microglia, inhibition of SENP6 may be a crucial beneficial therapeutic strategy for ischaemic stroke." (PMID 35869493, 2022).
asthma (20 papers, 2017 to 2025). "Furthermore, the findings in this study indicated that serum ANXA1 concentration represents a biomarker for asthma, which has potential utility as a diagnostic tool." (PMID 29301525, 2018). "Furthermore, ANXA1 and miR-196a-2 could be used as diagnostic biomarkers for asthma and therapeutic targets in the future." (PMID 36459329, 2022). "In addition, experimental studies have shown that ANXA1 is associated with asthma development." (PMID 29301525, 2018). "Many studies have demonstrated its important role in asthma, and even suggested ANXA1 as a therapeutic target for this pathology." (PMID 38542471, 2024). "Further investigation of the biological function of ANXA1 revealed that it interacts with genes enriched for asthma (including IL4 and IL13) and inflammatory regulation (NR3C1, glucocorticoid receptor)." (PMID 37227431, 2023). "Protein-protein network analysis demonstrated that ANXA1 interacts directly with genes enriched for asthma (including IL4 and IL13) and inflammatory regulation (NR3C1, glucocorticoid receptor) showing its significance in dysregulation of the immune response." (PMID 37227431, 2023). "The elevated levels of proinflammatory mediators correlated with exacerbation of eosinophil accumulation and subsequent airway remodelling, suggesting a beneficial role of AnxA1 or its mimetic peptide in the treatment of severe asthma." (PMID 35269381, 2022). "Of therapeutic interest is a report that the Annexin A1 peptide mimetic, Ac2-26, exerted multifaceted inhibitory effects on airway inflammation and hyper-responsiveness in a rat model of asthma." (PMID 35563776, 2022). "On the other hand, plasma levels of AnxA1 were lower in patients with asthma exacerbation than in patients with stable asthma, thus indicating a correlation between lower levels of the protein AnxA1 and bronchial asthma severity." (PMID 35269381, 2022). "Using a mouse model, we evaluated ANXA1 expression and levels in the blood of asthmatic patients and evaluated the relationship between ANXA1 levels and clinical profiles in asthma." (PMID 29301525, 2018). "ANXA1 levels were decreased in smokers or patients with asthma, cystic fibrosis, and rheumatoid arthritis." (PMID 29301525, 2018). "In this study, total and phosphorylated ANXA1 levels were increased in a mouse model of asthma and in inflammatory, endothelial, and epithelial cells." (PMID 29301525, 2018). "In this study, plasma ANXA1 levels were increased in patients with asthma but decreased in patients with exacerbated asthma." (PMID 29301525, 2018). "In contrast, decreased levels of LXA4 and annexin A1 (ANXA1) have been found in pediatric patients with asthma and wheezy infants." (PMID 29544524, 2018). "The reduced levels of lipoxin A4 (LXA4) and ANXA1 were reported in wheezy infants and patients with severe asthma." (PMID 29301525, 2018). "Annexin A1, A2 and A5 have a role in the regulation of inflammation activation and may serve as the potential biomarkers for asthma." (PMID 41550933, 2025). "We identified a potential five-biomarker panel (BPIFA1, MUC5AC, CAMP, CTSG, and ANXA1) that illustrates the inflammatory activity of asthma in sputum and could improve asthma phenotyping, providing valuable insights into personalized treatment approaches." (PMID 38542471, 2024). "Corticosteroids (a mainstay of asthma treatment) increase the synthesis of ANXA1." (PMID 37227431, 2023). "The ANXA1 locus was the only GWAS-significant locus that had not previously been associated with asthma or atopic traits, with one previous study showing an association with FEV1/FVC and bronchodilator response in smokers." (PMID 37227431, 2023). "Thus, our findings corroborate the proposition that the AnxA1 peptide Ac2-26 holds promise as an innovative therapy for the treatment of asthma." (PMID 35269381, 2022). "For instance, changes in miR-196a-2 expression and serum ANXA1 levels may play a role in asthma etiology." (PMID 36459329, 2022).
asthma (continued). "ANXA5 and ANXA1 (Annexin A1 protein) have also been proposed as potential biomarkers in asthma." (PMID 35628512, 2022). "In addition, the role of AnxA1 in allergic inflammation has been demonstrated in studies using ovalbumin-induced asthma in mice." (PMID 30650525, 2019). "Annexin A1 (AnxA1) levels are also decreased in patients with asthma, and in wheezy infants." (PMID 31396220, 2019). "One such study showed an association between the pathogenesis of asthma and a decrease in endogenous AnxA1 levels in the lungs, but not of its mRNA, probably related to cleavage of the protein to a 33 kDa isoform." (PMID 30650525, 2019). "ANXA1 levels were also correlated with lung function, suggesting that ANXA1 may be a potential marker for asthma." (PMID 29301525, 2018). "In this study plasma levels of ANXA1 were increased in asthmatic patients compared with healthy control subjects, which is similar to the findings of other studies, suggesting that ANXA1 has compensatory anti-inflammatory effects in asthma." (PMID 29301525, 2018). "However, larger numbers of asthmatic patients are required for prospective studies, and further studies are warranted to investigate the potential mechanism of ANXA1 in asthma." (PMID 29301525, 2018). "In addition, there was a significant relationship between ANXA1 and lung function in asthmatic patients, indicating that ANXA1 is potentially involved in the pathogenesis of asthma." (PMID 29301525, 2018). "But increased plasma ANXA1 level in stable asthma is decreased in exacerbated asthmatics, indicating that circulating ANXA1 may be decreased due to ANXA1 increase in target inflammatory site in exacerbated state of asthma." (PMID 29301525, 2018). "In addition, receptor FPR2 expression was increased in OVA-challenged mice, suggesting that ANXA1 may be involved in asthma pathogenesis." (PMID 29301525, 2018). "However, the exact role of ANXA1 in asthma remains to be determined." (PMID 29301525, 2018). "However, some relevant studies in asthma suggest that Anxa1 may play a role in AR." (PMID 33193578, 2020). "Previous studies have reported that Anxa1 and FPR2 play an important role in the pathogenesis of asthma." (PMID 33193578, 2020). "However, the role of ANXA1 in the pathogenesis of asthma is not clear." (PMID 29301525, 2018). "Additionally, they showed that annexin A1 (ANXA1) protects against bronchial epithelial injury by increasing PTEN and FAK expression and inactivating PI3K/Akt pathway, suggesting that restoring PTEN expression might prevent bronchial epithelial apoptosis in asthma." (PMID 35814272, 2022).